HGF (hepatocyte growth factor)
Diseases named in the same sentence as HGF in open-access papers (continued):
Sharing a sentence is not in itself a finding about the gene and the disease.
cancer (continued). "In contrast, a large number of studies have shown that HGF/c-MET activation affects cancer prognosis, but we found a significant relationship only in a small number of cancers by comparing HGF/c-MET expression and survival prognosis in 11 cancer patients." (PMID 34261467, 2021). "The hepatocyte growth factor/c-Met (HGF/c-Met) pathway is a key mediator in the mesenchymal-epithelial transition, a process required for the invasion of blood or lymph vessels by cancer cells as a preliminary step to migrate cancer cells to distant organs." (PMID 34200439, 2021). "In many carcinomas, together with TGF-β and interleukins signaling, hepatocyte growth factor (HGF), basic fibroblast growth factor (bFGF), epidermal growth factor (EGF) and PDGF also play a role in the induction of transcription factors responsible for EMT progression." (PMID 33407613, 2021). "Although these pro-HGF activating proteases are tightly regulated by two transmembrane serine protease inhibitors, HAI-1 and HAI-2, downregulation of HAIs has been observed in several cancers and has been shown to induce progression." (PMID 32290402, 2020). "IPA analysis of the differentially expressed genes showed significant downregulation of a number of pathways involved in cancer progression, including cellular migration and invasion, integrin signaling (integrin β3), STAT3 and growth factor signaling (HGF, PDGF, and IGF)." (PMID 32352029, 2020). "As previous studies have suggested that the possible effects of MACC1 on cancer cell proliferation are mediated via the HGF/c-Met signaling pathway, we explored whether the MACC1-induced effects on OS were mediated via the HGF/c-Met pathway." (PMID 33425885, 2020). "Similar to HGF/Met signaling, deregulation of FGFR signaling can lead to cancer progression." (PMID 31940827, 2020). "Studies have shown that the hepatocyte growth factor (HGF)/mesenchymal epithelial transition (c-Met) signaling pathway plays a key role in growth, invasiveness, metastasis, and acquired drug resistance of cancers of digestive system." (PMID 33195182, 2020). "Additionally, tyrosine kinase signaling by hepatocyte growth factor (HGF) and its receptor tyrosine kinase (MET/HGFR) is hyperactivated in numerous cancers, inducing proliferation, invasion, and metastasis." (PMID 33194736, 2020). "The HGF/SF-MET signaling plays a major role in promoting cellular proliferation, motility, migration, survival, and angiogenesis, all of which are essential factors for cancer progression." (PMID 33217986, 2020). "The role of HGF/MET signaling in the immune system in cancer is gaining attention since it could constitute a mechanism of primary and acquired resistance to cancer immunotherapy." (PMID 33276788, 2020). "Despite the large number of clinical and preclinical trials worldwide, no significant positive success in the use of anti-HGF/c-Met treatments on cancers of the digestive system has been achieved." (PMID 33195182, 2020). "Several HGF/MET-neutralizing antibodies and MET kinase-specific small molecule inhibitors have been developed, resulting in some context-dependent progress in multiple cancer treatments." (PMID 32435640, 2020). "This study shows that cell migration was induced by GAS6 and HGF in some cancer cell lines but not in others through Boyden chamber assays." (PMID 32055714, 2020). "In summary, our data show that the GAS6-AXL and HGF-MET signaling axes play a critical role in cancer cell migration and invasion, demonstrating that simultaneous inhibition of these pathways contributes to the anti-cancer effects of cabozantinib." (PMID 32055714, 2020). "The binding of HGF to its receptor leads to dimerisation and phosphorylation of c-MET and subsequent activation of several signalling pathways including MAPK and PI3K that regulate proliferation, invasion, and migration of cancer cells." (PMID 33271944, 2020). "HGF/MET has oncogenic and pro-metastatic effects, but also has anti-cancer functions." (PMID 32435640, 2020).
cancer (continued). "Colon CAFs specifically secrete growth factors, like hepatocyte growth factor (HGF), which activates mitogen-activated protein kinase (MAPK) and phosphatidylinositol 3-kinase (PI3K)/AKT pathways responsible for cell survival and invasion of the cancer." (PMID 32641866, 2020). "The regulatory role of HAI-2 in the activation of pro-HGF by inhibiting the activating proteases (including matriptase), which induces HGF/MET signaling axis, has been considered a major suppressive function in cancer progression." (PMID 32290402, 2020). "Cancer stimulates stromal cells to also produce a huge number of growth factors that support neoplastic cell proliferation (i.e., TGF-β, epidermal growth factor (EGF), hepatocyte growth factor (HGF) or fibroblasts growth factor (FGF), and Wnts." (PMID 31979112, 2020). "Hepatocyte growth factor (HGF) and its physiological receptor tyrosine kinase MET have been reported to be involved in acquired resistance to various TKIs and have been seen as critical targets in cancer therapy." (PMID 32041944, 2020). "Despite the promise of targeting the HGF-c-Met signaling pathway for cancer therapy, no specific therapeutic agent has been approved for clinical use." (PMID 32182714, 2020). "Later on, the enhanced expression of the SASP factors CXCL12, HGF, MMPs and TGFβ in irradiated fibroblasts was reported to increase EMT and invasiveness of cancer cells, and enhanced expression of the SASP factors EGF, FGF-4, GM-CSF, IGF-1,2, IGFBP-2,4,6 induced chemoradioresistance in cancer cells." (PMID 32384619, 2020). "HS has been shown to interact with growth factors including fibroblast growth factors (FGFs), hepatocyte growth factor (HGF), insulin-like growth factors (IGFs) and transforming growth factor β (TGFβ), and promotes cancer cells adhesion, migration/invasion and angiogenesis." (PMID 31898491, 2020). "The selective inhibition of MET activation has been anticipated to become a molecular-targeted therapy of cancer, although no selective inhibitors of HGF-MET have been approved as drugs for cancer." (PMID 33121208, 2020). "HGF and its physiological receptor tyrosine kinase MET have been reported to be involved in acquired resistance to various tyrosine kinase inhibitors and have been proposed as critical targets in cancer therapy." (PMID 32245422, 2020). "In cancer, the EMT phenotype is also mediated by a series of cell-cell signaling pathways, such as the Wnt, TGF-β, insulin growth factor, and hepatocyte growth factor (HGF) signaling pathways." (PMID 32944388, 2020). "Later on, many studies showed that HGF and MET were often expressed in a large variety of cancers." (PMID 31547040, 2019). "Also, myeloid cells have been shown to induce EMT-like properties in cancer cells via TGFβ, EGF, and HGF." (PMID 31772577, 2019). "The role of HGF/c-Met and BDNF/TrkB signaling is reported in several cancers including HCC." (PMID 30885237, 2019). "When the process was examined using cancer cells treated with the malignant ascites preincubated with the antibodies neutralizing the mediators of EMT, the invasiveness of A2780 cells was significantly reduced upon the neutralization of HGF and TGF-β1." (PMID 30609691, 2019). "HGF is among the most important growth factors that are secreted by PSCs in response to the stimulus received by PDAC cell and can, in turn, induce growth and drug resistance in cancer cells." (PMID 31072019, 2019). "We evaluated the concentration of ANG-2, FGF-2, HGF, IL-8, PDGF-BB, TIMP-1, TIMP-2, TNF-α, and VEGF that are the major cytokines involved in angiogenesis in MM and other cancers and, as previously demonstrated in MM patients, directly correlate with disease activity and increase with progression." (PMID 30626425, 2019).
cancer (continued). "In our studies, the human cancer cell lines DU145 and MDA-MB-231 showed a strong reduction of c-Met phosphorylation, migration, and invasion when treated with the c-Met inhibitor BMS-777607 in the presence of commonly used concentrations of HGF (25–50 ng/mL)." (PMID 30719213, 2019). "We assumed EGF and HGF as inputs into the model, while activities of STAT3 and ERK indicated by their phosphorylated levels are considered as the main model outputs, which together regulate cancer cell proliferation and survival." (PMID 29920512, 2018). "In terms of cancer progression, PI3K-mediated activation of NOX is necessary to promote cell migration and chemotaxis in response to stimulants such as hepatocyte growth factor (HGF) and platelet-derived growth factor (PDGF)." (PMID 29868481, 2018). "We suggest that NAFLD patients or animals with cancer or individuals with the potential to have cancer are not appropriate for HGF treatment." (PMID 30083132, 2018). "HGF/Met signaling is not only a powerful stimulator of the invasion and metastasis of cells, but also allows for the survival of cancer cells in the bloodstream in absence of anchorage." (PMID 29854314, 2018). "Our studies raise the possibility that responses to TKIs may vary between different anatomical metastatic sites since the levels of HGF and/or NRG1β expression differ between sites to which HER2+ cancers may metastasize." (PMID 29550255, 2018). "IRCR201 does not inhibit the interaction between HGF and c-Met, but it exhibited excellent growth inhibition capacity in various types of c-Met-expressing cancer cell lines compared to huOA5D5.v2 in vitro." (PMID 28902178, 2017). "Binding of HGF to its receptor, MET, leads to receptor dimerization and induction of signaling pathways that support growth, survival, motility and metastatic spread of cancer cells." (PMID 28420162, 2017). "HGF reactivates MET, EGFR and RON phosphorylation and restores AKT, ERK and WNK1 signaling upon MET inhibition, promoting the survival of MET-inhibited cancer cells." (PMID 28968967, 2017). "Therefore, insufficient HAI-1 levels can result in enhanced HGF-MET signaling in PDAC, which eventually promotes chemoresistance and invasive growth of the cancer cells." (PMID 29202869, 2017). "Mostly recruited following a CXCL5 gradient (whose human orthologues, CXCL1 and IL‐8, are expressed by cancer cells), these immunosuppressive cells could in turn promote EMT‐like changes in cancer cells, via multiple pathways comprising TGF, EGF, and HGF." (PMID 28599100, 2017). "HGF-induced MET activation also triggers multiple pro-survival pathways in cancer cells, such as AKT and STAT3, promotes epithelial-mesenchymal transition (EMT), and thus confers primary and acquired resistance to anti-cancer therapy." (PMID 28420162, 2017). "Binding of HGF to its transmembrane cell surface receptor c-MET, which is expressed on cancer cells activates several intracellular cell-signalling pathways that play a pivotal role in cancer cell proliferation and migration." (PMID 29100344, 2017). "In the present study, TGFβ reduced HGF production in PSCs and reduced cancer cell mitogenesis and migration induced by the high HGF-producing PSCs concomitant with a reduction in phosphorylation of Gab1 and ERK in the cancer cells." (PMID 29069737, 2017). "Notably, elevated levels of heparanase are positively correlated with triggered expression of MMP-9, hepatocyte growth factor (HGF) and vascular endothelial growth factor (VEGF) that are entangled with cancer progression." (PMID 28359266, 2017). "Treatment of cancer cells with inhibitors of pro-HGF activation alone had no impact on the migration of EBC-1 cells." (PMID 28968967, 2017). "However, constitutive activation of the HGF/MET signaling pathway promotes the growth and survival of cancer cells and stimulates their metastatic spread." (PMID 28420162, 2017).
cancer (continued). "Thus, while HGF (or fibroblasts) do not further stimulate MET signaling or promote the viability in MET-amplified cancer cells, our results established that MET-amplified NSCLC cells become addicted to HGF upon pharmacological MET inhibition." (PMID 28968967, 2017). "Gefitinib also reduced the levels of β-catenin in cancer cells, however neither fibroblasts nor inhibitors of HGF/MET signaling had any effect on β-catenin levels in DiFi cells." (PMID 27121052, 2016). "The binding of MET with its ligand (hepatocyte growth factor) activates downstream signaling pathways, including phosphoinositide 3-kinase (PI3K)/Akt, Ras-Rac/Rho, MAPK, and phospholipase C-γ, frequently activated in human cancers." (PMID 26918450, 2016). "Fibroblast HGF activates Met in triple-negative breast cells, which mediates the survival of the cancer cells in the presence of the EGFR inhibitor gefitinib." (PMID 26828520, 2016). "Cancer cells with amplified MET, which normally display HGF-independent MET activation, become dependent on HGF when MET kinase activity is inhibited, suggesting that HGF may also be associated with resistance to drugs that target MET." (PMID 27121052, 2016). "We found that EFE significantly inhibited the HGF-induced motility of MDA-MB-231 cells in a concentration-dependent manner, thus confirming that EFE possesses inhibitory activity against HGF-induced cancer cell motility." (PMID 26943796, 2016). "By inhibiting both ligand-dependent and c-Met overexpression-induced signaling in broad types of cancer cells, ABT-700 differentiates from other therapeutic agents targeting the HGF/c-Met axis including the recently disclosed antagonistic IgG4 c-Met targeting antibody LY2875358." (PMID 26879245, 2016). "Hepatocyte growth factor/ scatter factor (HGF/SF), insulin-like growth factor II (IGF-II), and autotaxin which are among several factors reported to contribute to cancer cell motility might be targeted by B1 AMCE but further clarification is required." (PMID 27558166, 2016). "Nevertheless, to the best of our knowledge, there is no report describing the role of Ran in HGF-Met-mediated signaling in the progression of human cancer." (PMID 27716616, 2016). "This type of neutrophil may contribute to cancer progression, since it produces growth factors such as vascular endothelial growth factor (VEGF), hepatocyte growth factor (HGF), MMP9, Bv8, and also have the capability to suppress cytotoxic lymphocytes." (PMID 27863478, 2016). "Like cancer cells, ASC secret many angiogenic factors including VEGF, hepatocyte growth factor (HGF) and fibroblast growth factor (FGF), which stimulate neovascularization in vivo and vascular network formation in vitro and widely used to establish an in vitro angiogenic model." (PMID 27167204, 2016). "The role of HGF/SF and MET in cancer has been brought to light by several studies." (PMID 27055285, 2016). "Moreover, the therapeutic rationale of dual targeting of HGF/c-MET and other signaling pathways by small molecules is a current option for many cancers." (PMID 28536400, 2015). "In line with this, previous studies demonstrated that IL-6 expression might be inhibited by Jagged-1 and HGF in macrophages, or by IDO in DC, though IDO presents the opposite effect in human cancer cells." (PMID 26060498, 2015). "HGF-induced FAK phosphorylation simultaneously upregulates many matrix metalloproteinases like MMP-1, -9, and -14, through activation of the transcription factor Ets, in cancers of the gallbladder, prostate, and liver thereby facilitating cancer invasion." (PMID 26404380, 2015). "Moreover, a HGF/c-MET specific antagonist, NK4, has been found to inhibit markedly the fibroblast-induced invasion of cancer cells, both in vitro and in vivo, although this has yet to be translated into the clinical setting." (PMID 26013123, 2015).
cancer (continued). "HGF makes the cancer cells independent of EGFR signaling and enables EGFR to interact with other proteins such as CUB domain-containing protein-1 (CDCP1), EphA2 and AXL, forming a c-Met (HGFR)-EGFR cross-talk that can't be inhibited by EGFR TKI treatment." (PMID 26405162, 2015). "In malignant tumors, HGF is produced by stromal cells, while its receptor c-MET is expressed by cancer cells, which in the mid-1990s led to the hypothesis that this paracrine loop might determine malignant behaviors." (PMID 28536400, 2015). "A possible CAF-triggered secretion of HGF, TGF-β or bFGF by cancer cells cannot be excluded as a contributory cause of the observed effects." (PMID 25880005, 2015). "Promotion of cancer EMT program and cell migration by HGF depends on c-Met." (PMID 25965999, 2015). "This suggests that the HGF/Met and downstream PI3K/AKT signaling may be potential therapeutic targets against chemoresistant cancers." (PMID 26115510, 2015). "As expected, CM from HGF siRNA treated cells failed to rescue cancer cells from the apoptosis by CPT-11." (PMID 26090722, 2015). "RAF inhibitors were found to elicit innate resistance via secretion of the growth factor HGF by stromal cells, resulting in ERK and PI3K-AKT activation and therapy resistance; these results suggest a potential for the concurrent application of RAF and HGF/MET inhibitors in CRC and other cancers." (PMID 26299805, 2015). "To investigate cell proliferation effects of c-MET inhibition by INC280, we tested the proliferation rates of untreated OVCAR3, SKOV3 and CaOV3 cancer cells, as well as the normal ovarian surface epithelium HOSE 6.3 cells, with HGF, HGF + INC280, and INC280 treatments." (PMID 26138303, 2015). "HGF over-expression has also been demonstrated to be sufficient for neoplastic transformation in cells expressing normal levels of wild type MET, and HGF over-expression in transgenic mice drives the development of multiple cancers." (PMID 28548073, 2014). "HGF-induced MET activation as a mechanism of attenuated sensitivity to cetuximab in CRC has been reported by preclinical studies using either CRC cell lines or, more recently, CRC spheroids enriched in cancer stem cells." (PMID 24811491, 2014). "Should HGF- or MET-directed therapy prove to be an effective treatment option for patients with GEC, experience with other RTK inhibitors suggests that resistance will invariably develop even in the subset of cancers that initially derive clinical benefit." (PMID 24930887, 2014). "Vice versa, the CAFs can also secrete similar growth factors, such as hepatocyte growth factor (HGF), keratinocyte growth factor (KGF), and insulin-like growth factors 1 and 2 (IGF-1 and -2), to stimulate the cancer cells to form malignant phenotype such as MICs." (PMID 24587996, 2014). "Expression of HGF and/or its receptor MET is increased in a wide variety of cancers." (PMID 28548073, 2014). "Recently, the ability of SAIT301 to inhibit HGF-induced invasion and migration of nasopharingeal cancer cell lines has been described, suggesting a potential use for MET inhibitors in the treatment of this highly invasive and metastatic type of cancer." (PMID 28548076, 2014). "HGF-MET signaling has been described as one of the inducers of the epithelial to mesenchymal transition (EMT), which leads to the reversible acquisition of an invasive and motile phenotype in carcinoma cells." (PMID 25230070, 2014). "In contrast, HGF plays common roles in cancer metastasis, independent of the presence or absence of MET mutations." (PMID 23296269, 2013). "Levels of HGF and LIF were significantly higher in patients with pancreatic malignancy." (PMID 23672538, 2013). "The involvement of HGF/c-Met signaling in hematogenous dissemination of cancer cells, however, has never been previously reported." (PMID 23723997, 2013). "Additionally, there is convincing evidence from murine derived cancer cells that p170 c-MET is exposed at the cell surface, and can be activated by HGF." (PMID 22511956, 2012).